AHNAK (AHNAK nucleoprotein)
Diseases named in the same sentence as AHNAK in open-access papers (continued):
Sharing a sentence is not in itself a finding about the gene and the disease.
Obesity (9 papers, 2015 to 2025). Accumulation of substantial excess body fat. "Mice with the functional knock-out for AHNAK nucleoprotein gene, a gene associated with calcium homeostasis, are resistant to high-fat diet-induced obesity." (PMID 27933298, 2016). "As males are more susceptible to metabolic diseases, AHNAK could be a potential sexually dimorphic protein in the male risk for obesity if the mouse findings here are corroborated in human tissue." (PMID 40181252, 2025). "The AHNAK nucleoprotein has been determined to exert an anti-obesity effect in adipose tissue and further inhibit adipogenic differentiation." (PMID 33785868, 2021). "We previously reported that AHNAK-KO mice are protected from diet-induced obesity, which was associated with differences in urine and blood metabolomic profiles between HFD-fed wild-type and AHNAK-KO mice." (PMID 26466345, 2015). "Collectively, our data show that AHNAK promotes adipose tissue development and obesity by potentiating BMP4/SMAD1 signaling and that AHNAK can serve as a novel regulator of metabolic homeostasis." (PMID 26466345, 2015). "Results from this study demonstrated that AHNAK downregulation protects mice from obesity, hepatosteatosis, and insulin resistance." (PMID 26466345, 2015). "Previous findings have demonstrated elevated AHNAK levels in WAT from mice with genetically or environmentally induced obesity." (PMID 26466345, 2015). "To study the potential correlation between AHNAK expression and obesity in humans, we analyzed existing GEO data." (PMID 26466345, 2015). "Future studies focused on how AHNAK levels and its modulation may relate to diet induced obesity to help determine if AHNAK could be a therapeutic target for metabolic syndrome." (PMID 40181252, 2025). "The AHNAK protein regulates fat cell development, and mice lacking AHNAK are less susceptible to obesity after being fed a HFD." (PMID 33785868, 2021). "Recent evidence has suggested that AHNAK expression is altered in obesity, although its role in adipose tissue development remains unclear." (PMID 26466345, 2015). "Thus, alternatively genetic regulation of AHNAK may be involved in altered adipose tissue-derived exosome mediated cell-cell communication relevant for obesity." (PMID 40671801, 2025). "Although the precise molecular mechanism underlying AHNAK involvement in β-adrenergic signalling remains to be determined, downregulation of AHNAK may be a new approach to increase the response to β-adrenergic stimulation and energy expenditure in adipose tissue, thereby treating obesity." (PMID 26987950, 2016). "Moreover, it should be determined whether AHNAK overexpression contributes to aggravated obesity and metabolic homeostasis." (PMID 26466345, 2015). "Although Ahnak KO mice showed strong resistance to diet-induced obesity and hepatic steatosis, the role of AHNAK in the regulation of hepatic steatosis has not been studied." (PMID 33785868, 2021).
laryngeal carcinoma (8 papers, 2013 to 2022). Carcinoma that arises from the laryngeal epithelium. "Upregulation of AHNAK was significantly associated with poor prognosis of laryngeal carcinoma, mesothelioma, and pancreatic ductal carcinoma." (PMID 32904605, 2020). "In this study, we identified AHNAK as a novel independent prognostic factor for the overall survival of larynx carcinoma patients." (PMID 23409183, 2013). "Here, we investigated the role of AHNAK in the pathophysiology of larynx carcinoma-one of the major subtypes of head and neck cancer." (PMID 23409183, 2013). "In our study, we analysed the expression levels of AHNAK by immunohistochemistry in tumor tissues from 83 larynx carcinoma patients." (PMID 23409183, 2013). "To this end, we analysed AHNAK expression in tumor tissues from 83 larynx carcinoma patients in relation to overall survival." (PMID 23409183, 2013). "Next, we determined the expression of AHNAK at protein level by immunohistochemical analysis of tissue microarrays (TMAs) from 83 larynx carcinoma patients." (PMID 23409183, 2013). "Moreover, AHNAK overexpression predicts poor clinical outcome in larynx carcinoma patients and reduced actin cytoskeleton dynamics and suppression of cell migration was assessed recently by AHNAK knock-down in six metastatic tumor cell lines." (PMID 36776379, 2022). "Next, we investigated the relevance of AHNAK, MIF and CD66b taken in combination regarding survival of larynx carcinoma patients." (PMID 23409183, 2013). "In further studies we sought to confirm the relative values of AHNAK, MIF and CD66b as prognostic markers in larynx carcinoma by multivariate survival analysis using Cox regression model." (PMID 23409183, 2013). "This study investigated the relevance of AHNAK, MIF and tumor-infiltrating neutrophils (CD66b-positive cells) for the survival of patients with laryngeal carcinoma-a major subtype of head and neck cancer." (PMID 23409183, 2013). "In further studies, we determined whether there might be a relationship between expression levels of AHNAK, MIF or CD66b and 5-years overall survival of larynx carcinoma patients." (PMID 23409183, 2013). "Additionally, these findings suggest that AHNAK might 'cooperate' with MIF and/or neutrophils to enhance progression of larynx carcinoma." (PMID 23409183, 2013).
neuroblastoma (7 papers, 2007 to 2025). Neuroblastoma (NB) is the most common solid, extracranial childhood tumor. "AHNAK mutations have been reported in other entities of neuroendocrine neoplasms (neuroblastomas and adrenocortical carcinomas, both with a frequency below 5%28), whereas BCOR mutations have been previously found in siNETs with a frequency of 5.6%29." (PMID 40410286, 2025). "AHNAK expression was higher in tumor cell-rich areas in high-risk neuroblastomas than in the lower risk groups." (PMID 34202325, 2021). "AHNAK shows intense and distinct staining in the tumor cell-rich regions in high-risk neuroblastomas in comparison to other risk groups (slight staining)." (PMID 34202325, 2021). "We identified AHNAK as a marker protein highly expressed in high-risk neuroblastoma, from which tryptic peptides have high intensity distributions in tumor cell-rich regions of sections analyzed by MALDI-MSI." (PMID 34202325, 2021). "AHNAK, downregulated in all the three contrasts, encodes a protein typically repressed in human neuroblastoma cell lines and in other types of tumors." (PMID 22646717, 2012). "The AHNAK gene encodes an unusually large protein that is typically repressed in cell lines derived from human neuroblastomas and in several other types of tumors." (PMID 22373165, 2011). "AHNAK is a huge protein (700 kDa) initially discovered in human neuroblastoma andskin epithelial cells, responsible for regulating cytoskeletal formation, muscleregeneration, calcium homeostasis, and signaling transduction." (PMID 39665079, 2024). "AHNAK has been described as a nucleoprotein that is significantly suppressed in neuroblastoma cell lines." (PMID 36557813, 2022). "The neuroblastoma-specific biological role of AHNAK has to be evaluated in subsequent detailed studies beyond the scope of this paper." (PMID 34202325, 2021). "AHNAK is an ubiquitously expressed giant protein, which has been found to be downregulated in several radiosensitive neuroblastoma cell lines." (PMID 17445279, 2007). "The AHNAK nucleoprotein and collapsin response mediator protein 1 (CRMP1) were identified as proteins associated with these peptide signatures, and their differential expression in the neuroblastomas of divergent risk was immunohistochemically validated." (PMID 34202325, 2021). "Interestingly, AHNAK peptide intensity in MALDI imaging of low- and intermediate-risk neuroblastoma sections was also occasionally high in areas with <80% tumor cell content." (PMID 34202325, 2021). "AHNAK has not been previously associated with neuroblastoma, but has been implicated in several cellular functions associated with cancer, including being listed one of six putative cancer genes involved in the evolution of nine cancer types across 3000 cancer genomes." (PMID 34202325, 2021). "Differential expression of the identified discriminative proteins, AHNAK and CRMP1, was immunohistochemically confirmed in sections, and discriminative spatial intensities of m/z peaks were validated in microarrayed tissue cores from tumor cell-rich regions in neuroblastomas." (PMID 34202325, 2021).
ovarian carcinoma (7 papers, 2014 to 2024). A malignant neoplasm originating from the surface ovarian epithelium. "TMEFF1 promotes cell proliferation, migration and invasion, inhibits apoptosis through MAPK and PI3K/AKT signaling pathways, and interacts with the tumor marker protein AHNAK in ovarian cancer." (PMID 38468232, 2024). "Knockdown of AHNAK in ovarian cancer cells was seen to activate the Wnt signaling pathway, and overexpression of AHNAK inhibited cell proliferation, migration, and EMT." (PMID 38033502, 2023). "Nevertheless, the function of AHNAK and Canonical Wnt cascade in ovarian cancer is poorly characterized at present." (PMID 34689136, 2021). "To further assess the biological impacts of AHNAK on ovarian cancer in vivo, we established a mouse xenograft model." (PMID 34689136, 2021). "The data illustrated that elevated content of AHNAK repressed the infiltration of ovarian cancer cells." (PMID 34689136, 2021). "Then, we overexpressed AHNAK in vitro and in vivo to establish the roles of AHNAK in ovarian cancer cell proliferation and metastasis." (PMID 34689136, 2021). "A cell proliferation assay was conducted, and the results demonstrated that AHNAK overexpression suppressed the cell proliferation of ovarian cancer cells." (PMID 34689136, 2021). "Gene Expression Profiling Interactive Analysis illustrated that AHNAK was downregulated in most cancers, including ovarian cancer." (PMID 34689136, 2021). "In summary, AHNAK levels in ovarian cancer are suppressed while AHNAK overexpression inhibits ovarian cancer progression by targeting the Canonical Wnt cascade." (PMID 34689136, 2021). "Further experiments illustrated that AHNAK overexpression dampened ovarian cancer cell proliferation along with infiltration in vitro and suppressed tumor growth and migration in vivo." (PMID 34689136, 2021). "Elevated AHNAK contents in ovarian cancer cell lines remarkably repressed ovarian cancer cell growth, along with metastasis in vitro, as well as in vivo." (PMID 34689136, 2021). "Elevated levels of AHNAK dramatically repressed ovarian cancer cell progression and metastasis in vitro as well as in vivo." (PMID 34689136, 2021). "To verify further AHNAK content in ovarian cancer, we collected 30 tumor serous ovarian cancer tissues and neighboring non-malignant tissues." (PMID 34689136, 2021). "The results indicated that AHNAK overexpression represses tumor growth along with migration in ovarian cancer." (PMID 34689136, 2021). "The authors hypothesized that AHNAK might regulate ovarian cancer progression through the Wnt pathway." (PMID 38033502, 2023). "It was found that AHNAK expression was downregulated in ovarian cancer." (PMID 38033502, 2023). "The interesting thing is that another report indicated AHNAK overexpression in ovarian cancer was associated with poor prognosis, yet in vitro, knockdown of AHNAK inhibited the proliferation, migration, and invasion of CAOV3 and SKOV3 cells in ovarian cancer." (PMID 38033502, 2023). "Moreover, AHNAK suppressed the progress of ovarian cancer partly via dampening the Canonical Wnt cascade." (PMID 34689136, 2021). "We established that AHNAK was downregulated in ovarian cancer." (PMID 34689136, 2021). "Moreover, the CCK-8 data illustrated that AHNAK overexpression dramatically repressed the proliferation of ovarian cancers." (PMID 34689136, 2021). "Herein, we illustrated that AHNAK was downregulated in ovarian cancer." (PMID 34689136, 2021). "Furthermore, we conducted a Transwell assay to assess the function of AHNAK in infiltration of ovarian cancer cells." (PMID 34689136, 2021). "The results illustrated that AHNAK was downregulated in ovarian cancer tissues, indicating that AHNAK could be a tumor suppressor and could play a vital role in ovarian cancer progress." (PMID 34689136, 2021). "Moreover, AHNAK suppressed the progress of ovarian cancer partly via inactivating the Canonical Wnt cascade." (PMID 34689136, 2021).
ovarian carcinoma (continued). "Nevertheless, the mechanism of AHNAK in ovarian cancer is still unclear." (PMID 34689136, 2021). "Therefore, AHNAK may be a biomarker and treatment target for ovarian cancer." (PMID 34689136, 2021). "Therefore, AHNAK might be a marker, as well as treatment target for ovarian cancer." (PMID 34689136, 2021). "We demonstrated that AHNAK content was lower in ovarian cancer in contrast with the non-malignant tissues." (PMID 34689136, 2021).
liver cancer (6 papers, 2018 to 2023). An epithelial or non-epithelial malignant neoplasm that arises from the liver. "Collectively, highly expression of AHNAK is associated with the occurrence of liver cancer, which is helpful to the early detection and diagnosis." (PMID 30259695, 2018). "Finally, promoter methylation and mRNA expression of AHNAK gene in liver cancer and adjacent tissues were determined by quantitative polymerase chain reaction (Q‐PCR), and the diagnostic value of AHNAK methylation level in hepatopathy was evaluated by receiver operating characteristic (ROC) curve." (PMID 30259695, 2018). "In liver cancer, our previous research found that the mRNA expression of AHNAK was elevated in liver cancer tissues and the methylation level of AHNAK decreased from liver disease to HCC." (PMID 36557813, 2022). "Next, an investigation of AHNAK mRNA expression was conducted in 60 cases of liver cancer tissues and adjacent tissues, and the methylation level of AHNAK promoter in PBMC was determined in 260 cases with different liver diseases." (PMID 30259695, 2018). "Higher mRNA expression of AHNAK was found in liver cancer tissues than that of adjacent tissues (P < 0.001), and the methylation level in PBMC decreased with the progression of hepatitis B‐related liver disease." (PMID 30259695, 2018). "The results revealed that liver cancer tissues had significantly higher AHNAK mRNA expression than the adjacent tissues (P < 0.001)." (PMID 30259695, 2018). "In addition, AHNAK mRNA had been reported to be overexpressed in liver cancer tissues by qPCR and the cancer genome atlas (TCGA) data." (PMID 34745991, 2021). "However, the function and mechanism of AHNAK in liver cancer require further study." (PMID 30259695, 2018). "In liver cancer, RNF38 was shown to induce cellular EMT by promoting TGF-β signaling through AHNAK ubiquitination and degradation." (PMID 34689136, 2021). "Therefore, this study utilized co-immunoprecipitation (Co-IP) and liquid chromatography coupled with tandem mass spectrometry (LC-MS/MS) to analyze the AHNAK interactome in liver cancer and matched paracancerous (MPC) tissues, aiming to investigate the AHNAK involving signaling pathways." (PMID 36557813, 2022).
breast tumor (5 papers, 2014 to 2021). "The up-regulated genes include CTNNB1, GSC and TWIST1, encoding for transcription factors known to be activated during breast tumor metastasis, and AHNAK and AKT1, variously involved in tumorigenesis and cell motility." (PMID 24962430, 2014). "We also found higher expression of AHNAK in human breast tumor samples compared to normal tissue." (PMID 27374178, 2016).
hepatocellular carcinoma (5 papers, 2019 to 2023). A malignant tumor that arises from hepatocytes. "Furthermore, AHNAK knockdown restored the reduced migratory and invasive capacity of HCC cells due to RNF38 downregulation, which appears to indicate the presence of AHNAK as an oncogenic factor in hepatocellular carcinoma." (PMID 38033502, 2023).
mesothelioma (5 papers, 2020 to 2024). A usually malignant and aggressive neoplasm of the mesothelium which is often associated with exposure to asbestos. "Migration and invasion of the other seven mesothelioma cells were significantly elevated compared to the AHNAK-deficient MeT-5A cell line, although knockdown of AHNAK significantly inhibited the migration and invasion of the seven cells." (PMID 38033502, 2023). "AHNAK was proposed as a biomarker for bladder urothelial carcinoma and is strictly related to cell migration in mesothelioma." (PMID 39201484, 2024). "AHNAK is a large scaffold protein that has been shown to regulate the proliferation, migration and invasion of mesothelioma, triple negative breast cancer and pancreatic cancer cells." (PMID 33564071, 2021). "In the study they examined AHNAK expression in eight mesothelioma cell lines and found that seven mesothelioma cell lines (211H, H28, H226, H2052, H2452, MESO1, and MESO4) had high AHNAK expression, and only MeT-5A had no detectable AHNAK expression." (PMID 38033502, 2023).
pancreatic ductal adenocarcinoma (5 papers, 2020 to 2021). An infiltrating adenocarcinoma that arises from the epithelial cells of the pancreas. "In recent years, it has been demonstrated that AHNAK serves as a novel prognostic biomarker in different types of cancer, such as pancreatic ductal adenocarcinoma, triple-negative breast cancer, and BC." (PMID 33456631, 2020). "AHNAK, a MYOF-interacting protein, mediates epithelial-mesenchymal transition, and its overexpression is correlated with the unfavorable outcome of pancreatic ductal adenocarcinoma." (PMID 34957301, 2021).
glioblastoma (4 papers, 2019 to 2024). The most malignant astrocytic tumor (WHO grade IV). "Moreover, the prognosis of glioblastoma patients with AHNAK mutations is worse (median survival of 4.16 months for AHNAK mutated patients compared to 13.53 months for wild-type AHNAK patients), which has been confirmed to act as an independent factor for poor prognosis in GBM." (PMID 38033502, 2023). "Comparing 1464 EMT-associated genes in glioblastoma with the pan-cancer dataset, we uncovered three key genes: VIM, EMP3, and AHNAK." (PMID 38229014, 2024). "AHNAK was previously identified to be deiminated in aggressive glioblastoma cells by our group." (PMID 32411128, 2020). "Finally, we identified AHNAK which is discussed as a tumor suppressor as the first paucimannose-carrying protein in glioblastoma and show the involvement of AHNAK in the observed paucimannose-dependent effects." (PMID 31320997, 2019). "Interestingly, U-138 MG cells express significantly more AHNAK than U-87 MG cells, further confirming the role as a tumor suppressor in glioblastoma (data not shown)." (PMID 31320997, 2019).